ALB (albumin)
Diseases named in the same sentence as ALB in open-access papers (continued):
Sharing a sentence is not in itself a finding about the gene and the disease.
hypothyroidism (continued). "In hypothyroidism, there is low plasma volume, high vascular permeability, lower synthesis and catabolism rates of albumin, and prolonged passage time through the extravascular spaces causing increased albumin mass in the extravascular space." (PMID 34786222, 2021). "After PPI network construction, the top five hub genes associated with hypothyroidism were extracted, including ALB, MAPK1, SPP1, PPARG, and MIF, whereas those associated with hyperthyroidism were ALB, FCGR2B, CD44, LCN2, and CD74." (PMID 32500465, 2020). "Specifically, the hypothyroidism and hyperthyroidism group share the same hub gene ALB, also known as albumin." (PMID 32500465, 2020). "Our PCA–logistic regression analysis results demonstrated that serum creatinine, blood urea nitrogen, blood uric acid, total protein, albumin, and anti-ribonucleoprotein antibody were important clinical variables for LN patients with hypothyroidism." (PMID 32357838, 2020). "Low albumin and enhanced cellular uptake of thyroxine by phagocytic cells results in hypothyroidism." (PMID 30640950, 2019). "Patient 3, with an increased IgG index, normal albumin quotient, and significantly increased IgG fraction in the Reibergram (~50%) also showed atrophic alterations in the context of hypothyroidism." (PMID 28008318, 2016). "It is important to point out that women included here were the non-GDM controls for a nested case-control study on GDM which included women who were obese, as well as those with conditions that may affect albumin metabolism, such as hypothyroidism." (PMID 37932245, 2023). "Furthermore, hyperthyroidism fosters albumin synthesis and secretion, and the contrary is observed in hypothyroidism." (PMID 33765288, 2021). "Also, we are unaware of any diseases (e.g., hyper- and hypothyroidism) that may perturb normal albumin metabolism, which may impact the accurate measurement of glycated serum protein levels." (PMID 31089471, 2019). "The first round of multivariate analysis identified the following prognostic indicators: age > 55 years, female sex, hypothyroidism, cardiac valve disease, dilated pupil(s) at admission, IVH, albumin > 14 g/L, DCI, and early infarction." (PMID 39775311, 2025). "Patients with hypothyroidism also had lower eGFRcre, 24hrCcr, urinary CER, serum albumin, and HbA1c levels." (PMID 36832157, 2023). "Hypothyroidism induced by PTU significantly increased AST, ALT, ALP, creatinine, BUN, and MDA concentration and noticeably reduced albumin, total protein, total thiol level, and SOD and CAT activity." (PMID 37144592, 2023). "We applied PCA–logistic regression analysis to demonstrate that three PCs—namely, PC1, PC2 and PC9, which included SCr, BUN, UA, TP, ALB, and anti-RNP antibody—were found to be important clinical variables with respect to LN patients with hypothyroidism." (PMID 32357838, 2020). "Consequent upon these highlighted discrepancies in data we planned to compare various lipid parameters, HbA1c and uric acid and albumin creatinine ratio among subjects with euthyroidism, SCH and overt hypothyroidism." (PMID 29805408, 2018). "The multiple linear regression analysis revealed explanatory variables with urinary CER, including age, sex, body mass index, 24 h Cr clearance (24hrCcr), and albumin while hypothyroidism was not considered an independent explanatory variable." (PMID 36832157, 2023). "Concentrations of AOPP before albumin correction were significantly lower in dogs with hypothyroidism in comparison to dogs with non-thyroid diseases (P = 0.031) and healthy dogs (P = 0.0143)." (PMID 36732758, 2023). "Additionally, hypothyroidism and low T3T4 groups had lower levels of serum albumin than that of the normal thyroid function group (19.01 ± 4.56 g/L vs. 28.68 ± 6.19 g/L, P < 0.05; 19.48 ± 3.99 g/L vs. 28.68 ± 6.19 g/L, P < 0.05; respectively)." (PMID 31015507, 2019).
hypothyroidism (continued). "Our analytical results showed that PC1, PC2, and PC9 were the PCs that have a significant influence on whether LN was combined with hypothyroidism —that is to say, SCr, BUN, UA, TP, ALB, and anti-ribonucleoprotein (RNP) antibody might be paramount factors in treating LN with hypothyroidism." (PMID 32357838, 2020). "While higher amounts of serum thyroxine are bound to TBG and serum albumin, the loss of the two carrier proteins in urine among children with NS interferes with the total serum thyroxine level but does not affect the accuracy of serum FT4 in diagnosing hypothyroidism." (PMID 38373933, 2024).
periodontitis (53 papers, 2007 to 2025). An acute or chronic inflammatory process that affects the tissues that surround and support the teeth. "In this study, we also analysed the abundance of proteins, such ashaptoglobin, S100A9 and Albumin, all previously linked to periodontitis." (PMID 40230956, 2024). "This study analyzed the salivary proteomics, adiponectin and albumin, related to weight loss and periodontitis in patients undergoing bariatric surgery." (PMID 37047877, 2023). "A previous study demonstrated that severe periodontitis was associated with systemic changes in total globulins, albumin, and cholesterol in cats." (PMID 33059691, 2020). "Similarly, the inverse association between serum albumin and periodontitis observed in our analysis is consistent with current evidence." (PMID 41463003, 2025). "Oxidative stress has been identified as a pivotal pathophysiological change associated with periodontitis, and albumin may play a protective role in periodontal tissues by participating in redox reactions, thereby helping to prevent periodontal damage." (PMID 40290655, 2025). "The association between serum neurofilament light chain (sNfL) and periodontitis remains unclear, and there is a need to examine the contribution of serum albumin (SA) in this association." (PMID 38864919, 2024). "However, their study also showed that severe periodontitis was significantly associated with low serum albumin levels in univariate logistic regression analysis (odds ratio = 3.23, 95% confidential interval [CI]; 1.16–8.96, p = 0.02)." (PMID 31382656, 2019). "Mediation analysis showed that TG, HDL-C, ALB, UA, CRP, WBC, and neutrophil count significantly mediated the association of CircS with periodontitis." (PMID 40672423, 2025). "The potential of targeted neutrophil and albumin mechanisms, in conjunction with the utilization of biomaterials, as therapeutic interventions for periodontitis have been a subject of exploration." (PMID 40290655, 2025). "Individuals with periodontitis exhibited higher white blood cell counts and lower serum albumin levels, consistent with a heightened systemic inflammatory state." (PMID 41463003, 2025). "Alterations in serum albumin levels, precipitated by periodontal disease and its concomitant therapeutic interventions, have concomitantly been shown to indicate an inverse correlation between serum albumin levels and chronic periodontitis." (PMID 40290655, 2025). "Passive smoke exposure leads to elevation of salivary markers related to periodontitis including IL-1beta, albumin and AST levels." (PMID 39835314, 2024). "Contradictory results have been reported about the relationship between severe periodontitis with low albumin levels." (PMID 37047877, 2023). "Salivary protein and albumin were positively correlated with periodontal patients, which demonstrated that the increase in salivary protein concentration in individuals with gingivitis or periodontitis was caused by plasma protein leakage." (PMID 37047877, 2023). "Various salivary antioxidants, such as superoxide dismutase, albumin, and ascorbic acid, have been used as markers for the diagnosis of periodontitis." (PMID 36498715, 2022). "In this study, pregnant women with periodontitis (OP and NP groups) had higher levels of Albumin when compared to their respective controls (OWP and NWP groups, respectively)." (PMID 36355174, 2022). "The article that analyzed albumin concentration found that CKD patients with periodontitis had lower albumin levels, indicating that their health was at risk." (PMID 35225864, 2022). "Albumin and Thioredoxin were up-regulated in periodontitis cases, while Cystatins (mainly S, SA, SN) and Lactotransferrin were down-regulated." (PMID 36355174, 2022). "The results of the present study showed an inverse independent relation between periodontitis and albumin levels." (PMID 34603867, 2021).
periodontitis (continued). "The finding that albumin concentration was increased in patients with total and severe periodontitis is in agreement with previous research." (PMID 31122214, 2019). "This would explain why the mean albumin concentration was particularly high in patients with severe periodontitis, which is generally characterized by active inflammatory processes, often reflected by increased gingival bleeding." (PMID 31122214, 2019). "Albumin concentration, chitinase activity and protease activities were significantly different across all three periodontitis groups (p < 0.001, p = 0.008 and p = 0.018, respectively)." (PMID 31122214, 2019). "The results showed lower serum albumin levels in chronic periodontitis patients compared to periodontally healthy subjects." (PMID 35919773, 2018). "This study showed an inverse relationship between serum levels of albumin and chronic periodontitis; i.e., lower serum levels were reported in subjects with chronic periodontitis." (PMID 35919773, 2018). "Decreases and increases in serum albumin levels under the effect of periodontal disease and its treatment indicated an inverse relationship between the albumin levels of serum and chronic periodontitis." (PMID 35919773, 2018). "The mean serum albumin levels in the healthy subjects and in the periodontitis group were 4.47±0.276 and 4.61±0.273 mg/dL, respectively." (PMID 35919773, 2018). "All the patients diagnosed with chronic periodontitis exhibited significant increases in serum albumin levels three months after treatment (3.78±0.33 mg/dL) (P<0.01)." (PMID 35919773, 2018). "Several studies concluded that there is an inverse relationship between albumin level and periodontitis." (PMID 30622957, 2018). "Serum level of albumin (P=0.02) and ferritin (P=0.043) in patients with periodontitis was significantly higher than that in patients with gingivitis." (PMID 29399214, 2017). "Participants with moderate or severe periodontitis were older, more likely to be men, were more often married, unemployed or retired, had higher serum albumin levels, and had survived treated with dialysis for longer." (PMID 28532432, 2017). "In a longitudinal study of 600 subjects, it was found that patients with a serum albumin concentration below 4.0 g/dL had significantly higher rates of periodontitis than patients with a serum albumin concentration above 4.0 g/dL." (PMID 28326084, 2017). "Similar changes in α-amylase, Ig heavy chain, and albumin (along with decreased cystatin levels) in saliva from patients with chronic periodontitis and gingivitis have also been noted in independent proteomic studies." (PMID 24944840, 2014). "Additionally, lower serum albumin concentrations have been reported in individuals with chronic inflammatory diseases, including periodontitis." (PMID 41463003, 2025). "Conversely, chronic periodontitis may impair chewing efficiency and nutrient intake, aggravate nutritional deficits and reduce serum albumin levels." (PMID 41463003, 2025). "This may result in lower serum albumin concentrations in patients with periodontitis compared to periodontally healthy individuals." (PMID 41463003, 2025). "Our data highlighted that bariatric and periodontitis patients presenting similar albumin levels, indicating that weight loss was not improved by low-grade inflammation." (PMID 37047877, 2023). "Moreover, increased levels of salivary albumin levels have been reported in patients with periodontitis." (PMID 37834046, 2023). "It is difficult to speculate whether the serum albumin concentration is genuinely affected by the inflammatory component of periodontitis or the individuals' general health or nutritional status." (PMID 34603867, 2021). "Also, serum FrAm is significantly influenced by serum protein concentration, particularly albumin which is reportedly lower in periodontitis patients." (PMID 31998807, 2020).
periodontitis (continued). "A previous study reported that urinary albumin excretion increases in patients with periodontitis, and another study conducted in Korea demonstrated that individuals with albuminuria were likely to exhibit a higher prevalence of periodontitis." (PMID 31015837, 2019). "Moreover, serum albumin levels in HD patients with treated chronic periodontitis were significantly lower (p = 0.023) than in untreated patients." (PMID 31382656, 2019). "However, certain variables were included in few articles such as family history of periodontitis (11, 3.1%), genetics (11, 3.1%), C-reactive protein (9, 2.6%), creatinine (5, 1.4%), and albumin (2, 0.6%)." (PMID 30622957, 2018). "Iwasaki et al14 reported an inverse relationship between periodontitis and albumin serum levels." (PMID 27651883, 2016). "Periodontitis increases systemic inflammatory burden leading to worsening of CKD which in turn has been has been found to negatively affect CKD of patients on hemodialysis therapy by altering their serum albumin and C-reactive protein levels." (PMID 24353542, 2013). "It is known for example that the level of alpha-2-macroglobulin, alpha-1-antitripsin, elastase and also albumin in saliva may be good indicators of gingivitis and/or periodontitis." (PMID 19424479, 2008). "Moreover, patients undergoing hemodialysis with periodontitis had lower serum albumin levels." (PMID 40290655, 2025). "As such, albumin may act as a bi-directional marker, linking poor nutrition and periodontitis." (PMID 41463003, 2025). "Moreover, periodontitis may amplify systemic endothelial injury, indirectly lowering albumin via the acute-phase response." (PMID 41463003, 2025). "Thus, it was hypothesized that smoking has effects on periodontal inflammation, and, therefore, serum ALP levels could indicate the current periodontal disease activity and serum albumin levels the general health status in periodontitis patients." (PMID 34603867, 2021). "Thus, it can be hypothesized that lower serum albumin concentration might have possibly been affected by the inflammatory component of periodontitis." (PMID 34603867, 2021). "However, studies evaluating the association between serum albumin and smoker with (or) without periodontitis are scarce." (PMID 34603867, 2021). "Indeed, patients with severe periodontitis had a higher mean percentage of bleeding on probing compared to patients without severe periodontitis, indicating active inflammation and thereby increased leakage of proteins such as albumin." (PMID 31122214, 2019). "Serum albumin and serum ALP levels can be detected in patients with generalized chronic periodontitis and used as biomarkers." (PMID 34603867, 2021). "Indeed, the augmentation of systemic markers due to periodontitis, such as specific interleukins, fibrinogen, albumin, CRP, matrix metalloproteinase-9 or tumor necrosis factor-α, participate to the vascular endothelial weakening and its dysfunction and, therefore, can promote systemic diseases." (PMID 35096635, 2021). "However, the exact mechanism behind serum albumin-periodontitis link is unknown." (PMID 34603867, 2021). "Patients with periodontitis have higher levels of CRP and SAA and lower levels of serum albumin compared with healthy population." (PMID 28326084, 2017). "Data on the determinations of serum albumin, ALT, AST, glucose, total cholesterol, and total proteins observed in, in which the ALT values show non-significant differences in increasing order in relation to the days of exposure to periodontitis." (PMID 41259556, 2025). "Smokers with generalized chronic periodontitis had significantly lower serum albumin levels than non-smokers with the same condition." (PMID 40290655, 2025). "In univariate analyses, when comparing total periodontitis with mild/no periodontitis, albumin concentration, chitinase activity and protease activity were all significantly increased." (PMID 31122214, 2019).
periodontitis (continued). "In contrast to these findings, HD patients with moderate-severe periodontitis exhibited higher serum albumin levels (mean/SD; none or mild periodontitis: 3.7/0.4 g/dL and moderate or severe periodontitis: 3.9/0.4 g/dL)." (PMID 31382656, 2019). "Conversely, reduced serum albumin levels align with their role as a negative acute-phase reactant, suggesting that periodontitis may influence hepatic protein synthesis or increase albumin consumption during inflammatory processes." (PMID 41463003, 2025). "Serum albumin is a well-recognized negative acute-phase reactant, and multiple investigations have reported reduced albumin concentrations among individuals with greater periodontitis or poorer oral health." (PMID 41463003, 2025). "Thus, the study was designed to estimate and correlate the serum ALP and serum albumin levels in smokers and non-smokers with generalized chronic periodontitis." (PMID 34603867, 2021). "Furthermore, there was a significant correlation of increased serum ALP levels and decreased serum albumin levels in smokers with generalized chronic periodontitis compared to non-smokers." (PMID 34603867, 2021). "Although albumin could be used as a biomarker for oral SCC and chronic periodontitis, it still remains to be determined whether this Raman spectral feature is related to the pathological course of skin SCC or is an overlap with its nearby peaks around 1032 cm−1 as C-C stretching modes of keratin." (PMID 31151168, 2019). "In fact, a recent report indicated that serum albumin levels were not significantly different between dentate HD patients and edentulous patients (p = 0.761), or patients with healthy periodontium or gingivitis and those with periodontitis (p = 0.601)." (PMID 31382656, 2019). "Iwasaki et al14evaluated albumin, a negative acute phase protein, in patients with periodontitis and concluded that there might be an inverse relationship between periodontitis and albumin serum levels." (PMID 27651883, 2016). "The study aimed to compare the serum albumin and serum ALP levels in smokers and non-smokers with generalized chronic periodontitis." (PMID 34603867, 2021). "The present study evaluated and correlated the serum albumin and serum ALP levels between smokers and non-smokers with generalized chronic periodontitis." (PMID 34603867, 2021).